STAT3 (signal transducer and activator of transcription 3)
Diseases named in the same sentence as STAT3 in open-access papers (continued):
Sharing a sentence is not in itself a finding about the gene and the disease.
cancer (continued). "The majority of cancers have constitutive activation of STAT3." (PMID 31684144, 2019). "Sensitization of cancer cells to anti-cancer drug-induced apoptosis is related with down-regulation of apoptosis related proteins (Mcl-1 or Bcl-2) and inhibition of phosphorylation of STAT3." (PMID 31817696, 2019). "Both STAT3 and NF-κB are transcription factors selectively activated in cancer stem cells." (PMID 31360301, 2019). "In addition, elevated levels of STAT3 have been reported in several drug resistant cancer cells where inactivation of STAT3 reversed the drug resistant phenotype." (PMID 30674340, 2019). "The addition of microbubbles, or surpassing clinical diagnostic intensities resulted in increased permeabilization efficiency, reduced cell viability and a change in phosphorylation status of p38, ERK1/2, CREB, Akt, STAT3, ribosomal protein S6 and eIF2α in the cancer cells." (PMID 31284599, 2019). "The pivotal role of STAT3 in tumorigenesis has promoted a campaign in drug discovery to identify a number of small molecules compounds that directly inhibit the activity and function of STAT3 for use in cancer treatment and prevention." (PMID 31315217, 2019). "Furthermore, miRNAs are known to play important roles downstream of the IL-6/STAT3 signaling axis in various cancer types." (PMID 31878193, 2019). "Recently, poor prognoses in cancer patients with high STAT3 expression have been reported." (PMID 32257917, 2019). "We previously identified p-STAT3 as an early molecular target of MH in cancer." (PMID 31491838, 2019). "STAT3 has been reported to be over-expressed in cancer cells." (PMID 31766284, 2019). "Several studies have highlighted that plant-derived phytochemicals, such as Pterostilbene, Cryptotanshinone and Curcumin, suppressed STAT3 activation, thereby reduced cancer cell proliferation and have been proposed as possible adjuvants of conventional chemotherapy." (PMID 31861720, 2019). "The most important proteins in all cancers are NF-κB and Stat3." (PMID 31658701, 2019). "STAT3 is a transcriptional factor that is constitutively activated in many cancer types." (PMID 31736743, 2019). "Hence, MDA-9 regulates stemness and PCSC chemoresistance not only though STAT3, but also through c-myc, connecting inherent resistance of cancer stem cells to chemotherapy with their capacity for self-renewal." (PMID 31878027, 2019). "The key driving pathways of CSCs, such as the PI3K/AKT/mTOR and JAK/STAT3 signals, were found to be significantly increased in cancers with high CSC properties, and hence investigations of many small molecules targeting such pathways are ongoing in clinical trials." (PMID 31861050, 2019). "We demonstrated that 2G8 treatment significantly reduced the activity of STAT3 in PDA cancer cells in vitro and in vivo by downregulating stromal IL‐6, and therefore, TGFβ is a potential target, the blocking of which can interrupt this stromal tumorigenic signal." (PMID 31609088, 2019). "We further found that knockdown of STAT3 or FOXL2 could significantly induce cancer cell apoptosis, indicating the importance of these two genes in cancer cell growth and apoptosis." (PMID 31221094, 2019). "Therefore, STAT3 has been validated as anti-cancer drug target and targeting STAT3 signaling is considered as a novel promising therapeutic strategy for eradication of HCC CSCs." (PMID 30709346, 2019). "To validate whether these genes are actually involved in JAK2/STAT3-mediated cancer cell stemness, we evaluated mRNA expression patterns in well-differentiated monolayer-cultured or CSC-enriched sphere-propagated HCT116 cells with or without JAK2 silencing." (PMID 31511084, 2019). "STAT3 is aberrantly activated in the aggressive cancers, hence a poor prognosis factor." (PMID 31360301, 2019). "Exosome-mediated transfer of particular microRNAs, including miR-193a-3p, miR-210-3p and miR-5100, could promote invasion of cancer cells by activating STAT3 signaling-induced EMT." (PMID 30866952, 2019).
cancer (continued). "In fact, elevated activation of STAT3 is observed in many types of solid and hematological cancers, and has recently been suggested as an important target molecule in the pre-therapeutic assessment of cancer patients." (PMID 31684051, 2019). "The aberrant expression and/or activities of several members of the STAT protein family, including STAT3 and STAT5A, have been implicated in the initiation, growth, and metastatic dissemination of various cancers, including head and neck, breast and brain cancers." (PMID 31783691, 2019). "In addition to the effects on α5β1-integrin and hyaluronic acid, resveratrol also inhibits the growth of cancer cells through apoptosis and downregulation of signal transducer and activator of transcription 3 (STAT3)." (PMID 31640297, 2019). "In vitro anti-cancer effects of the STAT3 pathway inhibitor were further evaluated on cell growth of human HCC cells by a MTT assay, on self-renewal capacity of HCC CSCs by the tumorsphere formation assay, and on cell cycle and apoptosis by flow cytometry analysis, respectively." (PMID 30709346, 2019). "Since the central role of STAT3 in carcinogenesis and chemoresistance, SLs able to switch off STAT3 signaling have gained considerable attention from the researchers for the development of a new therapeutic strategy for cancer treatment." (PMID 31781335, 2019). "Constitutive activation of STAT3/STAT5 has been identified in a wide range of human cancers." (PMID 31861720, 2019). "MicroRNAs are emerging as important regulators of STAT3 in the cancer pathogenesis." (PMID 31165412, 2019). "NF-κB and STAT3 cooperatively regulate several cytokines and chemokines including IL-6 16, which alone activates STAT3 and generates an IL-6/STAT3/NF-κB positive-feedback circuit, which plays a role in chronic colorectal inflammation and cancer." (PMID 31754344, 2019). "Notably, progranulin inhibition hampers STAT3 activation and cancer cell growth in both experimental systems." (PMID 31361391, 2019). "The blockade of the STAT3 pathway at a different level might thus benefit from combined approaches, approved or under investigation, targeting cancer cells and the cell of the microenvironment." (PMID 31438567, 2019). "Collectively, our results suggested that harmine might sensitize the anti‐cancer activity of AZD9291 via the STAT3/Met pathway in EGFR wild‐type NSCLC cells." (PMID 31454149, 2019). "Furthermore, pectolinarigenin markedly impaired cancer cell migration and invasion by down-regulating phosphorylated-Stat3, and expression of matrix metalloproteinase (MMP)-2, MMP-9, while up-regulating the expression of TIMP2." (PMID 31649548, 2019). "In this context, we examined whether the anti-cancer effect of PCT-209 involves the modulation of the STAT3 pathway." (PMID 31695609, 2019). "Similarly, the overexpression of ITGA2 increased the phosphorylation level of STAT3 and protein level of PD-L1 in cancer cells, and these effects were diminished by STAT3 inhibitor treatment." (PMID 31818309, 2019). "Furthermore, it is interesting to note that Stat3 is an important gene for maintaining stemness, and Napabucasin was independently shown to block stem cell activity of cancer cells through targeting Stat3 activity." (PMID 31086186, 2019). "PAK4 maintains cancer stem cell phenotypes through Stat3 signaling." (PMID 31658701, 2019). "However, STAT3 activation can induce apoptosis under certain conditions in various cancer types including PCa." (PMID 31828111, 2019). "ROS generated by NOX enzymes induced activation of Stat3 and autophagy of cancer cells." (PMID 31019654, 2019). "Various STAT3 inhibitors have been studied to inhibit cell proliferation in cancer cell lines." (PMID 31105556, 2019). "Persistent activation of STAT3 cell signal is a common characteristic of various cancers." (PMID 31028131, 2019).
cancer (continued). "STAT3 could also provoke EMT in collaboration with active K-Ras by increasing Snail expression in cancer cells." (PMID 31341890, 2019). "Indeed, targeting of total STAT3 protein to proteasomal degradation was notable, hence suggesting that inhibition of STAT3 by carnosol involves a cancer-type specific mechanism(s)." (PMID 31456939, 2019). "Indeed, the oncogenic functions of STAT3 in HCC have been extensively reported with relation to cancer cell proliferation, anti-apoptosis, migration, invasion, angiogenesis, stemness properties and immune suppression." (PMID 31731457, 2019). "However, transfection of STAT3 CA or Src CA in H1299 cells increased the migratory ability of cancer cells following MEMA treatment by 64.47% and 75.56%, respectively, compared with the untreated cells." (PMID 31067694, 2019). "Data from clinical specimens and in vitro experiments confirm that the miR‐125b‐5p quantity is negatively correlated with progression, and the target protein that regulates the epithelial–mesenchymal transition (EMT)/cancer stem cells (CSC) potential in HCC is STAT3." (PMID 31065520, 2019). "In this study, we found that S100A7 was highly expressed in cancer cells and could be reduced by luteolin (Lu) and quercetin (Qu) through Src/Stat3 signaling." (PMID 31731716, 2019). "Constitutively activated STAT3 also plays a pivotal role in holding cancer stemness of HCC CSCs." (PMID 30709346, 2019). "Putting these evidences together, STAT3 is an important therapeutic target for cancer treatment." (PMID 31684051, 2019). "Compounds able to suppress STAT3 activation and, on the other hand, to modulate intracellular redox homeostasis may potentially improve cancer treatment outcome." (PMID 31781335, 2019). "Another commonly dysregulated pathway in cancer is the STAT3 signaling pathway." (PMID 31052435, 2019). "2-Ethoxystypandrone might be considered as a potential STAT3 signaling inhibitor for developing an anti-cancer agent molecularly targeting CSCs in HCC." (PMID 30709346, 2019). "As STAT3 is a well-known oncoprotein that is persistently activated in many cancers, including HCC, our findings suggest that repressing STAT3 phosphorylation may be another mechanism that is essential for miR-122 to suppress tumorigenesis." (PMID 30735121, 2019). "On the other hand, IL6 could activate STAT3, which was reported to promote the proliferation and metastasis of many cancers." (PMID 31709178, 2019). "Over-reacted STAT3 contributed to the pathology of chronic inflammatory diseases and cancer." (PMID 31341890, 2019). "The potential benefits of inhibiting STAT3 signaling have long been recognized in the cancer field." (PMID 30622697, 2019). "Stat3 protein is a regulator of cell survival, proliferation, differentiation and apoptosis; it also regulates cell adaptation to hypoxia by stimulating angiogenesis in several types of cancers." (PMID 31690341, 2019). "STAT3 signaling is a very common target for cancer treatment." (PMID 31719837, 2019). "Stat3/MMP-involved pathway is essential for cancer invasion and metastasis." (PMID 31649548, 2019). "Accumulating studies indicate that activation of Toll-like receptors (TLRs) promotes the development of cancer by activating nuclear factor-κB (NF-κΒ) pathway and the transducer signal transducer and activator of transcription 3 (STAT3) in colon, gastric and liver cancers." (PMID 31796027, 2019).
cancer (continued). "IL-6-linked JAK/STAT3 and PI3K/Akt signaling pathways have been implicated in cancer progression." (PMID 31252615, 2019). "BBR was shown to inhibit STAT3 activation in cancer cells and CD4+ T cells." (PMID 30894513, 2019). "One of the most well-defined regulatory circuits linking chronic inflammation and cancer is formed by two distinct but complimentary feedback regulatory loops involving either IL-6, NF-κB, and Lin28, let-7 miRNA or IL-6, NF-κB, STAT3, miR-21, miR-181b-1, and the tumor suppressor genes PTEN and CYLD." (PMID 31557902, 2019). "It becomes even more interesting considering that STAT3 signaling has been described to be responsible for the growth of stem-like cancer cells in different tumors and induce the expression of the stem cell marker CD133, similar to our observation in Ikk2ca expressing mice." (PMID 31546614, 2019). "Herein, both direct inhibition of STAT3 and activation of the endogenous inhibitors may be considered as potential STAT3-inhibiting strategies for developing novel cancer therapeutics." (PMID 31088482, 2019). "Considering the extremely low toxicity of MSM, it could be developed as a preventive agent for cancers harboring overexpressed and aberrantly activated STAT3." (PMID 31088482, 2019). "In this context, it is anticipated that an in-depth understanding of STAT3 pathway, its downstream targets and their contribution to cancer progression could allow for improved therapeutic agents and interventions." (PMID 30622697, 2019). "Most of the studies on STAT3 and miRNA regulation are in cancer cells." (PMID 31220137, 2019). "In this section, we introduce the roles of signal transducer and activator of transcription 3 (STAT3) in miRNA regulation as a well-studied example in cancer biology, because STAT3 is the member of the STAT transcription factor family most frequently implicated in cancer biology." (PMID 31878193, 2019). "In addition, STAT3 can promote mitochondrial functions required for cancer cell stemness and metabolism." (PMID 30614183, 2019). "STAT3 (Signal transduction and activator of transcription 3) is the aggregation point of many single gene signaling pathways, is activated at high frequency in a wide diversity of cancers, and is a promising molecular target for cancer treatment." (PMID 30893785, 2019). "We and others have shown that curcumin induces anti-cancer effects via STAT3 inhibition." (PMID 30871215, 2019). "Although aberrant activation of STAT3 or STAT5 has been reported in a variety of human cancers, determining the activation state of STAT3 or STAT5 may permit evaluating the clinical potential of JAK2 inhibitors." (PMID 30717771, 2019). "Therefore, targeting persistently activated STAT3 signaling is considered one of the important therapeutic options for cancer treatment." (PMID 31684051, 2019). "CDK5 prohibits DNA damage with STAT3 interaction in cancer cells." (PMID 31395805, 2019). "After co-culturing with PBMCs, there was a significant decrease in colony formation in STAT3 sh cancer cells with the treatment of PD-L1 Ab than other groups, suggesting that genetic downregulation of STAT3 can have positive impact on enhancement of anti-PD-L1 therapy." (PMID 31511071, 2019). "In one of the most frequently lost regions, in 9p11, microRNA-1299 is encoded, a negative CRC regulator of STAT3 that is essential for cancer progression to advanced malignancy." (PMID 31795313, 2019). "In addition, the results have implications in other signaling cascades that are regulated by STAT3 and related transcription factors in cancer and other inflammatory diseases." (PMID 31427481, 2019). "Moreover, xanthatin selectively inhibited the growth of cancer cells with constitutively activated STAT3." (PMID 30993883, 2019).
cancer (continued). "Phase I/II studies on the use of STA-21 for the treatment of psoriatic lesions and on OPB-31121 and OPB-51602 for the treatment of advanced cancers have been completed, revealing that all of these compounds are effective inhibitors of STAT3 phosphorylation and have acceptable safety profiles." (PMID 31588227, 2019). "Recent studies have disclosed that targeting STAT3 acetylation may be a potential therapeutic approach for treating cancer." (PMID 31088482, 2019). "CUR also modulates both AP-1 and STAT3 in cellular proliferation of cancer cells." (PMID 30890933, 2019). "Lu and Qu inhibit Src/Stat3/S100Ay signaling to decrease the metastasis of cancer cells." (PMID 31731716, 2019). "Moreover, STAT3 contributes to cancer cachexia enhancing tumorigenesis, metastasis, and immune suppression, mostly in tumors associated with a high prevalence of cachexia." (PMID 31013615, 2019). "In addition, genome silencing of phosphatases that play a role in dephosphorylation/inactivation of STAT3, such as those encoded by PTPR genes, can also result in constitutive activation of STAT3 in cancer." (PMID 31671769, 2019). "Therefore, inhibition of STAT3-DNA binding has been considered as a promising strategy to develop targeted cancer therapies." (PMID 31088482, 2019). "Deregulated STAT3 is oncogenic and has been shown to be involved in the regulation of various important functions such as cell proliferation, and differentiation in many cancer cells." (PMID 31058086, 2019). "Moreover, it has been suggested that amplification of FGFR is required for the signal transducers and activators of transcription-3 (STAT3) activation in cancers." (PMID 31242658, 2019). "In addition, the protein levels of STAT3 and p-STAT3 were 1.6- and 4.5-fold higher in carcinoma tissue than in control mucosa." (PMID 31781300, 2019). "To address this inconsistency, we performed a systematic analysis to determine whether STAT3 can serve as a prognostic marker in human cancers." (PMID 29423040, 2018). "The difference in the expression levels of pSTAT3 and its downstream targets involved in aggressiveness and chemoresistance of cancer cells (e.g., c-Myc) following STAT3 siRNA versus Stattic treatment is speculated to have a role in this observation." (PMID 30347860, 2018). "The Oncomine database was queried for STAT3 expression in cancer and normal tissues." (PMID 29423040, 2018). "STAT3 is an interesting therapeutic target in this context, and a further understanding of the reasons for divergent STAT3 signaling and the resultant cellular effects will be important for the development of therapeutic targets in each cancer subtype." (PMID 29890775, 2018). "In addition, experimental evidence demonstrated that combined proinflammatory cytokines such as IL-6 and TNF-α are critical for both inflammation and cancer by activating STAT3 and the NF-κB complex." (PMID 30116149, 2018). "However, constitutive hyperactivation of STAT3 has been observed in multiple human cancers, where it contributes to tumor development." (PMID 29848966, 2018). "Consequently, parthenolide inhibited the growth and migration of cancer cells that had constitutively activated STAT3." (PMID 29921758, 2018). "Stat3 is recognized as a transcription factor that modulates the transcription of various genes to regulate important biological functions, including cell proliferation, differentiation, survival, angiogenesis, immune response, and cancer survival." (PMID 30209296, 2018). "Accordingly, cancer cells dynamically exploit STAT3 activity to carry out transcriptional programs somehow contrasting and complementary, such as supporting survival and growth, dormancy and awakening, stem cell-like features, and inflammation, immune response, and immune evasion." (PMID 30231553, 2018). "This may in part be due to differences in STAT3 expression levels between primary keratinocytes and cancer cell lines." (PMID 29630659, 2018).